LNCPNKY (lncRNA POU3F2 adjacent neural key regulator)
Synonyms: pinky; PNKY
Gene: Long non-coding RNA gene on chromosome 6 (98,829,967 to 98,835,057, reverse strand). Ensembl gene ENSG00000283010.
Diseases named in the same sentence as LNCPNKY in open-access papers:
LNCPNKY is named in the same sentence as 5 diseases in open-access papers, as found by Europe PMC text mining. Sharing a sentence is not in itself a finding about the gene and the disease.
LNCPNKY shares sentences with these, for which no sentence is quoted: breast carcinoma (1 paper); breast tumor (1); cancer (1); colorectal cancer (1); tumor (1).